IL6 (interleukin 6)
Diseases named in the same sentence as IL6 in open-access papers (continued):
Sharing a sentence is not in itself a finding about the gene and the disease.
migraine (continued). "Interleukin-6 (IL-6) is both a pro-inflammatory and nociceptive molecule, that is involved in various headache models and migraine patients." (PMID 37940864, 2023). "Interleukin-6 (IL-6) is a pro-inflammatory cytokine that is found to be elevated during migraine attacks." (PMID 37072694, 2023). "Curcumin 8-week supplementation in migraine patients was associated with a reduction in CGRP, IL-6, severity, and duration of headaches compared to controls." (PMID 36678160, 2023). "During migraine attacks, pro-inflammatory factors such as interleukin-6 (IL-6) and interleukin-1β (IL-1β) are elevated in the serum of migraineurs." (PMID 37090989, 2023). "To investigate the effect of inhibiting glycolysis on the release of pro-inflammatory factors in migraine, we used WB to examine the expression of IL-1β and IL-6 in the medulla dorsal horn." (PMID 37090989, 2023). "Studies conducted on animal models have provided a possible link between IR and migraine, considering that several vascular mediators, interleukins or cytokines (TNF-α, C-reactive protein, IL-1β, IL-6, and IL-8), have an important role in both IR and migraine." (PMID 37886939, 2023). "The most relevant cytokines related to migraines include IL-1, IL-2, IL-4, IL-6, IL-10, TNF-α, and TGF-β." (PMID 35896985, 2022). "Several major cytokines, including IL-1β, IL-6 and tumor necrosis factor (TNF), have been thought to be linked to migraine pathophysiology, as their levels are altered in individuals with migraine." (PMID 35884650, 2022). "It was reported that several major cytokines, such as TNF-α, IL-1β, and IL-6, were elevated in patients during migraine attacks." (PMID 35928284, 2022). "On one hand, it was observed that female migraineurs have increased levels of pro-inflammatory cytokines (TNF-α, IL-1β, IL-6, IL-8) during both the migraine attack and the migraine-free period." (PMID 35456034, 2022). "Most recently, however, we showed that serum levels of proinflammatory biomarkers including CRP, TNF-α, interleukin-6, NO, and malondialdehyde positively correlated with number of migraine headache days per month." (PMID 34991456, 2022). "As histological examination is not feasible in humans, clinical studies examined monocytes in blood taken from the jugular vein during spontaneous migraine attacks instead, finding increased iNOS expression and higher levels of IL-1β and IL-6." (PMID 35650524, 2022). "In recent studies, high serum levels of IL-1β, IL-6, and TNF (proinflammatory cytokines) in patients with migraine indicated that migraine was associated with inflammation within peripheral endings of trigeminal ganglion sensory neurons." (PMID 33995549, 2021). "TNF-α and IL-6 levels were significantly higher in migraine patients compared to healthy controls during and between attacks." (PMID 34112082, 2021). "IL-6 is a pro-inflammatory cytokine that is upregulated in the serum and blood of migraine patients during an attack." (PMID 34256692, 2021). "A study based on migraine patients from China demonstrated that they had higher levels of IL-6, IL-1β, and TNF compared to healthy controls." (PMID 33020432, 2020). "The mean TNF-α levels were significantly higher in patients who had migraine (1.19 vs. 0.92 pg/mL; p < 0.001), and IL-6 levels were almost significantly different (9.23 vs. 5.47 pg/mL; p = 0.05) compared to these parameters in the controls." (PMID 32019484, 2020). "On the other hand, platelet-leukocyte aggregates count has been found to be higher in patients with migraine during the interictal period in comparison with control subjects, with a possible link to the release of IL-6 and cytokine tumoral necrosis factor-α." (PMID 33391152, 2020). "sCD40L stimulates the production of proinflammatory cytokines (IL-1, IL-6, IL-8, IL-10, TNF), which are pain mediators and are suggested to be implicated in neurovascular inflammation resulting in migraine pain." (PMID 33020432, 2020).
migraine (continued). "It is known that some adipokines (such as leptin and adiponectin), interleukin 6 (IL-6) and tumor necrosis factor alpha (TNF-α), can act as mediators of inflammatory processes linked to persistence and progression of migraine." (PMID 32349653, 2020). "A recent investigation found that serum interleukin-6 and other inflammatory mediators were increased in patients with migraine." (PMID 31824404, 2019). "TNFα, PGE2, IL-6, and IL-1β are proinflammatory cytokines which have been demonstrated in the process of migraine." (PMID 31428213, 2019). "IL-6 is an abundant prototype inflammatory cytokine, shown to be elevated in patients with the common forms of migraine." (PMID 28900389, 2017). "Concentration of IL-6 is increased during the first 2 hours of migraine; moreover, IL-10 and tumour necrosis factor alpha (TNF-α) are also elevated during attacks." (PMID 27191890, 2016). "Multiple neurotransmitters and hormones, including CGRP, substance P, neuropeptide Y, adiponectin, leptin, orexin-A, interleukin (IL)-1, IL-6, and TNF-α have been implicated in migraine pathogenesis." (PMID 23181051, 2012). "A preclinical in vivo migraine model was used to evaluate the effect of meningeal IL-6 application on mechanical withdrawal thresholds both to the face and hindpaws." (PMID 22273495, 2012). "Inflammatory and immune mediators, including TNF-α, IL-1, CGRP, orexin, and IL-6, are involved in migraine pathogenesis, and substance P, CGRP, and IL-6 are elevated during acute migraine attacks." (PMID 23181051, 2012). "This study provides direct evidence that IL-6 can sensitize dural afferents in a manner consistent with sodium channel phosphorylation and that it produces prolonged migraine-related pain behavior through activation of the ERK pathway." (PMID 22273495, 2012). "The finding of higher IL-6 in both headache groups is consistent with previous studies in migraine." (PMID 40236898, 2025). "This review of randomized trials highlights that elevated serum cytokines (particularly IL-1β, IL-6, and TNF-α) are associated with increased migraine frequency and may contribute to migraine chronification." (PMID 41377228, 2025). "Furthermore, the PI3K-Akt signaling pathway is an important survival signal transduction pathway in cells; when activated in the brain tissue of a rat migraine model, it involves seven targets, including Akt1, IL-6, and BCL2." (PMID 41009787, 2025). "IL-6 is an inflammatory cytokine that has been shown to both predict the emergence of a depression-susceptibility phenotype following CSDS and sensitize mice and rats to the emergence of migraine-like phenotypes when applied to the dura." (PMID 40634879, 2025). "If confirmed, these findings could have important implications for the use of anti-IL-6 therapies in specific populations, such as patients with migraine and glaucoma or pregnant women." (PMID 40858837, 2025). "Indeed, TNFα can sensitize nociceptors and induce pain, while IL-6 is elevated in some migraine patients, especially during migraine attacks." (PMID 41010614, 2025). "Another migraine-CSDS mechanistic link comes from studies of interleukin 6 (IL-6)." (PMID 40634879, 2025). "The same cytokines suffused during a migraine flare—IL-6, TNF-α, ROS—subvert antitumour surveillance; melatonin extinguishes these mediators, synchronises clock-gene–driven metabolism and stitches a biochemical thread between headache relief and cancer immunity." (PMID 40791587, 2025). "In migraine, activation of the immune-neurological system occurs, resulting in the release of pro-inflammatory cytokines such as tumor necrosis factor-alpha and interleukins, especially interleukin-1 beta and interleukin-6." (PMID 40427393, 2025). "Elevated levels of miR-197, miR-101, and miR-143, along with proinflammatory cytokines (TNF-α, IL-6, and IL-17A), align with the hypothesis of migraine as an inflammatory process." (PMID 41010614, 2025).
migraine (continued). "Compared to the control group, the migraine patients had increased levels of IL-6 in their blood." (PMID 39416954, 2024). "Likewise, circulating IL-1β, IL-6, or IL-8 levels are often enhanced in migraineurs compared to healthy controls, especially during the ictal stage of migraine, as recently shown by a meta-analysis." (PMID 38397400, 2024). "It has been suggested that PAR2 could be a therapeutic target for migraines, as its activation and IL-6 signaling could prime NO donors." (PMID 38836002, 2024). "In patients with gout, the deposition and phagocytosis of monosodium urate crystals in tissues activate the NLRP3 inflammasome, leading to the production of critical cytokines such as IL-1β, IL-6, and tumor necrosis factor (TNF)-α, which are implicated in the occurrence of migraines." (PMID 38202145, 2023). "Additionally, supporting a role for neurogenic inflammation in migraineurs, elevated levels of plasmatic IL-1β, prostaglandin E2, tumor necrosis factor-α (TNF-α), IL-6, or nitrite were observed during migraine attacks." (PMID 38062355, 2023). "sVCAM-1 levels have also been found significantly higher in subjects with more frequent migraine; in the same study, IL-6 was the only inflammatory mediator that was found to be higher in migraine patients than controls, when adjusting for age and sex, but without reaching statistical significance." (PMID 37176011, 2023). "It was observed that serum concentrations of IL-6 and NO, as well as the frequency, severity and duration of migraine attacks, were reduced in migraine patients who received cinnamon as compared with the placebo group, but CGRP levels did not change in either group." (PMID 36678160, 2023). "A 2015 study noted that migraine patients had higher IL6 levels compared to healthy controls." (PMID 35432179, 2022). "Moreover, intermediate-dose XZR had a similar beneficial effect, as it reversed the high levels of TNF-α (15.91 ± 6.93 pg/mg protein), IL-1β (38.20 ± 0.76 pg/ml), and IL-6 (17.76 ± 3.02 pg/ml) in rats with migraine (p < 0.05)." (PMID 35928284, 2022). "The aim of this study was to investigate whether functional polymorphisms in the IL-1 family (IL-1α, IL-1β and IL-1RN), IL-6 and TNF-α genes may influence the response to oral NSAID administration or triptans during migraine attacks." (PMID 36614097, 2022). "Interestingly, it is noteworthy that altogether, IL-6, nitric oxide pathway and cortical dis-excitability have been recognized as a critical moment in migraine pathophysiology." (PMID 34945208, 2021). "Additionally, this same dose of IL-6 given onto the dura is capable of sensitizing male and female rats to respond to subthreshold doses of migraine relevant triggers such as lowered dural pH and dural calcitonin gene-related peptide (CGRP)." (PMID 34256692, 2021). "In this regard, a significant increase in the peripheral levels of pro-inflammatory cytokines such TNF-α, IL-1β, IL-6 and IL-8—whose involvement in many autoimmune disorders is well known—have been found in migraine patients, both in interictal and ictal periods." (PMID 34749743, 2021). "The only stimulus tested was IL-6 and other migraine-relevant stimuli may lead to differential responses across the body; in particular, other stimuli applied to the lower body may lead to facial hypersensitivity." (PMID 34256692, 2021). "Furthermore, clinical studies elucidated the role of IL-6 and IL-8, which appeared significantly more expressed in patients with migraine than in healthy subjects." (PMID 34685736, 2021). "On the other hand, as mentioned, proinflammatory cytokines such as TNF-α, IL-1β and IL-6 could also affect nociceptive responses in the trigeminal pathway and play a role in migraine pain initiation." (PMID 32054443, 2020). "The role of IL-6 has been also demonstrated in neuroinflammation and specifically in migraine." (PMID 33146036, 2020).
migraine (continued). "This raises the possibility that circRNAs may regulate IL-6, IL-1 beta, and other inflammatory factors in order to influence migraine development." (PMID 33178826, 2020). "Additionally, proinflammatory cytokines, including IL-1β, IL-6, IL-8, and TNF-α have been implicated in migraine pain and are increased during migraine attacks." (PMID 32054443, 2020). "Platelets activation may be involved in triggering migraine attacks through 5-HT metabolism, NO, and a number of pro-inflammatory cytokines, including interleukins 1, 6, and 8 (IL-1, IL-6, IL-8) and TNF-α." (PMID 31722730, 2019). "Other studies support our findings of this pro-nociceptive role of BDNF in pain chronification, where spinal BDNF mediates prolonged PGE2 sensitivity in rodents primed with IL-6 and sequestering BDNF in the cisterna magna can prevent IL-6-mediated hyperalgesic priming in a model of migraine." (PMID 29394316, 2018). "First, we found that serum levels of classical pro-inflammatory IL-6 and IL-18 were higher in all patients with migraine, irrespective of the presence of the mutation." (PMID 28900389, 2017). "Furthermore, studies implicated several pro-inflammatory cytokines, such as IL-1 and IL-6, to be involved in migraine." (PMID 28900389, 2017). "IL-6 is a cytokine with an established role in modulating migraine." (PMID 27875242, 2017). "Intracranial interleukin-6 (IL-6) levels have been shown to be elevated during migraine attacks, suggesting that this cytokine may facilitate pain signaling from the meninges and contribute to the development of headache." (PMID 22273495, 2012). "Taken together, these studies led us to propose that increased levels of IL-6 in the meninges produces migraine-related pain behavior and this hypothesis was addressed using a preclinical model of headache." (PMID 22273495, 2012). "Interleukin-6 (IL-6), which is one such mediator found to be elevated during migraine attacks, is a cytokine with an established role in modulating various inflammatory pain conditions, including skin incision, carrageenan injection, burn-injury pain and pancreatitis-induced pain." (PMID 22273495, 2012). "Thus, accumulating evidence points to IL-6 as a contributing factor to many pain conditions possibly including migraine." (PMID 22273495, 2012). "This is supported by the findings showing that patients with migraines have higher levels of IL-6, interleukin 8 (IL-8), and tumor necrosis factor (TNF-α) compared to healthy individuals, indicating that these pro-inflammatory cytokines may play a role in the development of a migraine." (PMID 40002876, 2025). "After adjusting for IL-6 and TNF-α in the exploratory analysis, the positive effect of diet intervention on the severity of migraine and its comorbidities (except MSQ) was reduced, which supports our hypothesis that IL-6 and TNF-α partially mediated the causal pathway." (PMID 41473187, 2025). "For days with migraine in the past 4 weeks, the difference in the change from baseline between the sham diet and the true diet groups was significantly attenuated after adjusting IL-6 and TNF-α (i.e., p-value = 0.0098 for the unadjusted model vs. p-value = 0.0757 for the adjusted model)." (PMID 41473187, 2025). "Our results indicated that the effect of migraine in increasing the risk of AD development might be mediated by TNFα, while IL-1α, IL-1β, and IL-6 do not play a role in this process." (PMID 38903170, 2024). "Additionally, IL-6 levels were demonstrated to be correlated with migraine headache frequency." (PMID 38812640, 2024). "Furthermore, comprehensive genetic analysis using GWAS has identified not only genes encoding CGRP and 5-HT1F receptors but also genes involved in the production of TNF-α and IL-6 and regulating apoptosis and inflammatory responses as candidate genes for migraine." (PMID 37176049, 2023).
migraine (continued). "Considering the low expression of CD39 and CD73 in the CD62L-positive subsets of Tregs (‘naïve’ and CM), and the high level of IL-6 in migraine patients, it is possible that Th17 cells may mediate Th cell polarization in lymph nodes and mucosa-associated lymphoid tissues." (PMID 30319363, 2018). "Plasma cytokine levels have been studied previously in primary headache disorders, with higher levels of pro-inflammatory cytokines IL-6, IL-8, TNF-⍺, and IL-1β reported in migraine compared to healthy controls." (PMID 40991059, 2025). "Studies have shown that PTGS2 participates in the pathogenesis of migraines, and the symptoms of migraine patients can be improved by inhibiting the PTGS2 proinflammatory pathway and reducing the levels of TNF-α, IL-2, and IL-6." (PMID 41009787, 2025). "Nitroglycerin (NTG) triggers pathological vasodilation in the migraine mice model, accompanied by elevated Mt2, nitric oxide (NO), and pro‐inflammatory markers (CGRP, IL‐6, TNF‐α), alongside neuronal activation." (PMID 41194575, 2025). "Pro-inflammatory cytokines – such as IL-1β, IL-6, IL-8, and TNF-α – are often elevated interictally in migraineurs compared to non-migraine controls." (PMID 41377228, 2025). "At the end of 12 weeks, the true diet group had a larger reduction in questionnaires of migraine (except for MSQ), gastrointestinal symptoms, and poor sleeping, as well as food-specific positive IgG, IL-6, TNF-α, and CGRP in the serum." (PMID 41473187, 2025). "A recent meta-analysis found significantly higher circulating levels of C-reactive protein (CRP), IL-1β, IL-6, and TNF-α in patients with migraine relative to healthy individuals." (PMID 41377228, 2025). "Patients with chronic or frequent migraines tended to have higher pro-inflammatory cytokine levels (IL-6 and TNF-α) compared to those with episodic/less-frequent migraines." (PMID 41377228, 2025). "Pro-inflammatory cytokines, such as interleukin (IL)-1β, IL-6, and tumor necrosis factor (TNF)-α, rise during migraine attacks, sensitizing pain pathways and increasing gut permeability, worsening neuroinflammation." (PMID 40230722, 2025). "Based on this review, IL-6, IL-1β, and TNF-α stand out as the most plausible biomarkers for migraine chronification." (PMID 41377228, 2025). "Obesity is connected to increased levels of proinflammatory cytokines, such as IL-6 and TNF-alpha, and adipokines like leptin, which are known to activate the trigeminovascular pathways that play a role in migraines." (PMID 41278056, 2025). "Experimental validation confirmed Mt2's dual regulatory function: its inhibition reduced NOS2 expression—a key mediator of vascular tone—and concurrently decreased migraine‐related inflammatory markers, including CGRP, IL‐6, and TNF‐α." (PMID 41194575, 2025). "A meta-analysis revealed that serum levels of CRP, IL-1β, IL-6, and TNF-α were elevated in migraine patients compared to healthy controls." (PMID 40149800, 2025). "The serum level of IL‐1β, IL‐6, TNF‐α, and CGRP in the migraine group were significantly higher than the normal group." (PMID 41496770, 2025). "Neurogenic neuroinflammation has a wide role in migraine pathogenesis, with altered systemic immune responses occurring in migraine patients due to the release of pro-inflammatory cytokines, such as TNF-α and IL-6, both in ictal and interictal periods." (PMID 41473187, 2025). "Proinflammatory cytokines, including IL-1β, IL-6, IL-8, and TNF-α, are elevated during migraine attacks, sensitizing nociceptive pathways such as the trigeminal system." (PMID 40175732, 2025). "The endothelial‐specific knockdown of Mt2 suppressed neurovascular inflammatory cascades (NOS2, TNF‐α, IL‐6, CGRP), regulating the cerebrovascular tone and somatosensory cortical neuronal activation, contributing to the migraine‐like pain relief." (PMID 41194575, 2025).